INS (insulin)
Diseases named in the same sentence as INS in open-access papers (continued):
Sharing a sentence is not in itself a finding about the gene and the disease.
Hyperinsulinemia (continued). "Only patients who were homozygous for the 4G allele were at risk for MI with the greatest pro-insulin values, implying that PAI-1 genotype may alter the vascular risk associated with hyperinsulinemia." (PMID 35330428, 2022). "Together, these results suggest that chronic hyperinsulinemia leads to excess levels of ROS in insulin-resistant HepG2 cells, that high levels of ROS alter IR incorporation into clusters, and that antioxidants can partially rescue the behavior of IR-clusters as a consequence of reducing ROS levels." (PMID 36473871, 2022). "Because insulin-degrading peptide IDE is known to degrade insulin along with Aβ, in hyperinsulinemia, the binding of insulin to IDE may have interfered with Aβ degradation, leading to Aβ accumulation in the brain." (PMID 35958733, 2022). "Although we represent adipose metabolism through glycerol instead of FFA, the difference in dynamics we observe for insulin acting on glucose compared to insulin acting on glycerol likely reflects the extreme IR with compensatory hyperinsulinemia in our adolescent cohort." (PMID 35991189, 2022). "A disproportion between peripheral and hepatic insulin is created, which may lead to excess fat accumulation and peripheral hyperinsulinemia." (PMID 35784568, 2022). "Hyperinsulinemia is characterized by abnormally elevated levels of insulin in the body." (PMID 35454166, 2022). "Beyond signal transduction, we also demonstrated that hyperinsulinemia could directly reduce insulin‐stimulated glucose uptake, a function of insulin." (PMID 34921686, 2022). "Decreased pancreatic β-cell dysfunction, upregulated insulin expression and glucose-stimulated insulin secretion may result in hyperinsulinemia, leading to insulin resistivity for blood glucose." (PMID 36078079, 2022). "Although fructose does not acutely increase insulin levels, a chronic exposure indirectly causes hyperinsulinemia and obesity." (PMID 35565885, 2022). "Glucose levels were unaffected by both aldosterone and dexamethasone treatment, and aldosterone did not influence insulin levels, while dexamethasone caused hyperinsulinemia." (PMID 36034417, 2022). "Consequently, this results in abnormal insulin secretion from pancreatic β-cells and phosphomannomutase 2 hyperinsulinism (PMM2-HI)." (PMID 36726472, 2022). "Furthermore, the role of hyperinsulinism cannot truly be evaluated, because PCOS per se represents a natural predisposition to an impaired insulin pattern." (PMID 36140277, 2022). "Hyperinsulinism results from inappropriate insulin secretion during hypoglycaemia." (PMID 35294086, 2022). "Consequently, the pancreas has to secrete higher amounts of insulin, and this results in a state of hyperinsulinemia." (PMID 34940598, 2021). "In turn, this hyperinsulinemia will activate de novo hepatic lipogenesis which in contrast to other hepatic insulin-dependent pathways such as glucose production through gluconeogenesis, seems to remain insulin sensitive." (PMID 33669443, 2021). "Immunoassay results demonstrated marked hyperinsulinemia in all patients, and dilution of plasma revealed a high insulin/C-peptide molar ratio with an increase in insulin immunoreactivity following correction for dilution, characteristic of insulin-binding antibodies." (PMID 34051096, 2021). "The hyperinsulinemia in HFD-fed L-IDE-KO mice could theoretically be attributable to reduced hepatic insulin extraction and/or enhanced β-cell function and mass." (PMID 33477364, 2021). "Moreover, the increased TG was positively associated with the ratio of CD3+CD4+/CD3+CD8+, and was accompanied by reduced insulin sensitivity and hyperinsulinemia." (PMID 33935964, 2021). "A traditional view is that lower insulin sensitivity may be a driver of compensatory increases in β-cell function and hyperinsulinemia." (PMID 34867781, 2021).
Hyperinsulinemia (continued). "Previous studies have demonstrated that hyperinsulinemia may be responsible for the development of IR, a condition in which cells become less sensitive to insulin." (PMID 34566890, 2021). "Exogenous insulin and consequent hyperinsulinemia may activate some signaling molecules (such as PHLPP1 and Grb14) and influence hepatocyte apoptosis." (PMID 34118892, 2021). "As a reaction to the mentioned insulin refractory, hyperinsulinemia occurs." (PMID 33921222, 2021). "Apelin is also upregulated by hyperinsulinemia and important for insulin sensitivity maintenance." (PMID 34887778, 2021). "According to the authors, hyperinsulinemia-mediated islet and β-cell insulin/IGF-1 resistance may be involved in the decomposition of β-cells." (PMID 34208601, 2021). "Since the Na+/K+/ATPase pump and Na+ influx are stimulated by insulin, hyperinsulinemia could increase TauT efficiency, although direct experimental evidence for this is lacking." (PMID 34676442, 2021). "Indeed, physiological euglycemic hyperinsulinemia induced by insulin infusion (6 pmol/min/kg) in healthy volunteers acutely reduces urinary urate (25–35%), suggesting a key role for insulin in the pathogenesis of hyperuricemia." (PMID 34408667, 2021). "As metabolic mechanisms, it can be demonstrated that prolonged QTc interval may be due to increased FFA, insulin resistance, and hyperinsulinemia in more obese individuals." (PMID 34090333, 2021). "Plasma insulin levels are elevated during fasting due to elevated glucose beta-cell stimulation and or in response to meta-inflammation because even with average glucose values, there is hyperinsulinemia." (PMID 34220716, 2021). "ENaC channel activity is stimulated by insulin in the kidney; this may be an important link between kidney injury and the hyperinsulinemia observed in PCOS, enhanced by dysregulation in TMPRSS4." (PMID 33922918, 2021). "Hyperinsulinemia, defined by insulin secretion higher than normal relative to blood glucose levels, may be one proinflammatory factor associated with numerous ill health effects including heart disease and stroke." (PMID 33691751, 2021). "0602K reduced plasma insulin, whereas Lira further increased the hyperinsulinemia of db/db mice." (PMID 34022222, 2021). "It is suggested that insulin resistance leads to hyperinsulinemia, and insulin has both pro-mitotic and antiapoptotic activity that may assist in tumor progression." (PMID 34068325, 2021). "Notably, TRF increases whole-body insulin sensitivity, reduced hyperinsulinemia, restored diurnal clock gene expression rhythms in the tumor and non-tumor tissues, and attenuates insulin signaling." (PMID 33495474, 2021). "Drugs that reduce insulin (hyper) secretion, normalize pulsatile insulin secretion and/or increase hepatic insulin clearance may also have the potential to prevent or delay the progression of hyperinsulinemia-mediated diseases." (PMID 34360563, 2021). "During exogenous hyperinsulinemia, insulin production by the pancreas and the hepatic glucose production is blocked, and the amount of glucose administered reflects its tissue uptake, and, thus, indirectly insulin sensitivity." (PMID 34132976, 2021). "Also, the mode of suppression of the insulin transduction pathway in liver, muscle and adipose fat by primary hyperinsulinemia still remains unresolved." (PMID 34659123, 2021). "Moreover, hyperinsulinemia (resulting from subcutaneous insulin injection) stimulates hepatic expression of IGF-1 and elevates its bioavailability via depletion of IGFBP-1/2." (PMID 34535145, 2021). "In conclusion, the lower glucose levels after dexamethasone treatment could be attributed to hyperinsulinemia that may be due to both increased insulin resistance in muscle and increased sensitivity of pancreatic β cells to lower glucose levels." (PMID 35052508, 2021). "The other hypothesis is that hyperinsulinemia is a compensatory response to tissue decrease in insulin sensitivity." (PMID 34202289, 2021).
Hyperinsulinemia (continued). "The increased plasma glucose concentration during OGT might impair insulin response in ID if insulin resistance in peripheral tissues leads to excessive insulin secretion and hyperinsulinemia." (PMID 34105193, 2021). "Since activation of SIRT1 can lead to improved glucose tolerance and insulin sensitivity it is speculated that SIRT1/NF-kB/JNK axis could play an important role in regulating hyperinsulinemia and hyperglycemic in inflamed hepatocytes." (PMID 34034759, 2021). "Hyperinsulinemia is related to aging and may be the consequence of an increase in insulin secretion and/or a decrease in its clearance." (PMID 34054736, 2021). "Thus, due to a mitogenic effect of exogenous insulin in a mechanism similar to endogenous insulin, its overdosing, generating iatrogenic hyperinsulinemia, should be avoided." (PMID 33562380, 2021). "The high activity of this enzyme may interfere with insulin signaling, favoring resistance to the action of insulin, and hyperinsulinemia." (PMID 34124125, 2021). "We previously demonstrated that three weeks-FRD fed rats developed changes in liver glucose and lipid metabolism paralleling endocrine dysfunction (hyperinsulinemia, hyperleptinemia, higher plasminogen activator inhibitor-1 and lower adiponectin levels) and an insulin resistant state." (PMID 35056315, 2021). "Consequently, the human body increases the production of pancreatic insulin and results in hyperinsulinemia to compensate for the dysfunction." (PMID 34503545, 2021). "Insulin resistance can result in elevated rates of insulin secretion and hyperinsulinemia." (PMID 34022222, 2021). "In support of a role of hyperinsulinemia in atherosclerosis, it was recently reported that higher insulin levels in subjects with normal glucose tolerance were the best predictor of restenosis after previous revascularization by percutaneous coronary intervention because of ischemic heart disease." (PMID 34360563, 2021). "This hormonal overactivation can lead to abnormal metabolic activity that reduces pancreatic and digestive functionality but favors overproduction of insulin from the pancreas, exacerbating conditions of increased circulating insulin that typifies chronic hyperinsulinemia." (PMID 34497507, 2021). "Elevated peripheral insulin levels will sharply increase the brain and cerebrospinal fluid insulin levels, while prolonged peripheral hyperinsulinemia will downregulate the blood–brain barrier insulin receptors and inhibit the transport of insulin to the brain." (PMID 34055854, 2021). "Enhanced insulin production results in hyperinsulinemia that promotesde novo lipogenesis, hyperlipidemia, and adipose tissue expansion.Expanded adipose tissue supports local and systemic inflammation byenhancing pro-inflammatory mediators secretion, including cytokines,chemokines, and adipokines." (PMID 34236862, 2021). "Disruption of the insulin signaling pathway extends lifespan in several animal models and collectively these data suggest the distinct possibility that hyperinsulinemia might play a pivotal role in the aging process." (PMID 34360563, 2021). "Any dietary approach that causes weight loss improves hyperinsulinemia as body fat can only be stored, rather than oxidized in the presence of high insulin levels." (PMID 34360563, 2021). "In short, we need treatments that reverse the hyperinsulinemia resulting from impairments in insulin signaling or glucose metabolism, as hyperinsulinemia can hyperactivate uninhibited or partially inhibited insulin‐signaling pathways and provoke adverse effects." (PMID 34766133, 2021). "Visceral obesity is implicated in the development of T2DM through increased free fatty acid flux and increased triglycerides storage in other organs implicated in glucose metabolism, with secondary disturbance in insulin sensitivity, hyperinsulinemia, and beta-cell failure." (PMID 34202289, 2021).
Hyperinsulinemia (continued). "Third, since hyperinsulinemia in mothers with GDM might be often attributed to excessive insulin therapy, we cannot deny the possibility that insulin therapy during pregnancy influenced DNA methylation in cord blood samples." (PMID 34267729, 2021). "Hyperinsulinemia leads to increased androgen production, which, in turn, may impair insulin sensitivity." (PMID 34071499, 2021). "Indeed, hyperinsulinemia directly stimulates ovarian androgen production, which in turn alters insulin sensitivity with a positive feedback loop between insulin resistance and hyperandrogenism." (PMID 34342583, 2021). "In addition, during conditions of hyperinsulinemia, dysfunctional insulin clearance becomes evident, due to abnormal insulin degrading enzyme regulation." (PMID 34299321, 2021). "Hyperinsulinemia in AN patients may increase the binding of insulin and IGF-R and may also reduce IGF-binding proteins (IGFBPs), thus increasing biologically active IGF-1; this results in the development of hyperkeratosis and papillomatosis." (PMID 34438601, 2021). "Our results from the MD-Lipolysis study and the POEM study are consistent with the idea that elevated FFA levels, and not glucose, are the major metabolic derangement driving fasting hyperinsulinemia in obese insulin-resistant individuals with normal glycaemic control." (PMID 33712379, 2021). "This further increases circulating insulin levels, leading to hyperinsulinemia." (PMID 34940598, 2021). "Serum insulin were markedly elevated in db/db mice indicating hyperinsulinemia." (PMID 33986669, 2021). "It discusses how insulin might play a pivotal role in health, disease and longevity and (potential) strategies to prevent and manage hyperinsulinemia." (PMID 34360563, 2021). "In multiple logistic regression analysis, TG was significantly associated with the risk of hyperinsulinemia and increased CD3+CD4+/CD3+CD8+ ratio which was significantly negatively correlated with disposition index (DI30) and DI120, indicators for insulin sensitivity." (PMID 33935964, 2021). "Insulin signalling induces the expression of the insulin-degrading enzyme (IDE), which is involved in both insulin and Aβ degradation; hyperinsulinemia might determine a competitive inhibition for IDE-dependent Aβ degradation, leading to Aβ accumulation." (PMID 33597002, 2021). "To test whether hyperinsulinemia alone augments tumor growth in postmenopausal mice, we delivered exogenous insulin to lean mice by implanting osmotic pumps." (PMID 33495474, 2021). "It is still debatable if the reduction of insulin sensitivity leads to hyperinsulinemia or whether the increased insulin level during fasting and postprandial conditions could cause decrease of cell’s metabolic response to insulin." (PMID 33916952, 2021). "This may be due to hyperinsulinemia perceived in diabetic rats and a struggle between degradation of Aβ-42 and insulin for the same substrate, IDE." (PMID 34834352, 2021). "However, we, and others have previously suggested that HOMA-IR is a less reliable index of insulin sensitivity than the indices generated during hyperinsulinemia euglycemic clamps, OGTT or fast sample intravenous glucose tolerance tests." (PMID 33652807, 2021). "Hyperinsulinemia permits glycerol and FFAs to circulate to the hepatic tissue and further promote gluconeogenesis; glycolysis in muscle is enhanced by the high concentration of insulin and production of lactate." (PMID 34026558, 2021). "However, HFD modestly decreased liver clearance (p = 0.056) while increasing renal clearance by >50% (p < 0.01), suggesting a significant role for renal insulin clearance in limiting the hyperinsulinemia that accompanies HFD." (PMID 33466380, 2021). "Glucose levels might remain normal in PCOS despite IR because of the compensatory increase in pancreatic β-cell insulin production, resulting in hyperinsulinemia." (PMID 34484117, 2021). "HFD feeding increases renal insulin clearance to limit systemic hyperinsulinemia." (PMID 33466380, 2021).
Hyperinsulinemia (continued). "Notably, TRF increases whole-body insulin sensitivity, reduces hyperinsulinemia, restores diurnal gene expression rhythms in the tumor, and attenuates tumor growth and insulin signaling." (PMID 33495474, 2021). "However, in many cell types, compensatory hyperinsulinemia in insulin‐resistant states can bypass partial IR defects by activating “spare IRs,” that is, IRs present in excess of those needed to fully/strongly activate post‐IR processes." (PMID 34766133, 2021). "PW (300 mg/kg) improved hyperinsulinemia and enhanced insulin sensitivity." (PMID 34451554, 2021). "Previous study found insulin could stimulate theca cell androgen production, elevating serum free testosterone levels, so hyperinsulinemia will increase the local production of androgens." (PMID 34552564, 2021). "IDE plays an important role in insulin clearance, as evidenced by Ide gene ablation in mice, which resulted in impairment in the hepatic insulin clearance, followed by glucose intolerance and hyperinsulinemia." (PMID 34769364, 2021). "The growth of many tumors is spurred by insulin, and resolution of hyperinsulinemia by SH‐BC‐893 could also limit tumor growth." (PMID 34231322, 2021). "Additionally, the insulin pump therapy approach leads to the easier adjustment of insulin dosing and hyperinsulinemia prevention." (PMID 34362176, 2021). "Moreover, both hyperinsulinemia and the impairment of insulin response observed in FC and FF pregnant rats were also found, and even more marked, in their fetuses." (PMID 34684668, 2021). "Moreover, increased glucose level further stimulates the insulin secretion from pancreatic β-cells, resulting in peripheral hyperinsulinemia." (PMID 34684619, 2021). "Hence, lipid-enriched diets stimulate the release of insulin from the pancreatic β-cells lead to hyperinsulinemia." (PMID 34026558, 2021). "In hyperinsulinemia, the amount of insulin in the blood is higher than usual." (PMID 34203830, 2021). "Because liver-specific deletion of IDE (L-IDE-KO mouse) showed normal plasma insulin levels, the hyperinsulinemia seen in the IDE-KO might be due to alterations in the GLUT1/GLUT2 ratio in pancreatic β-cells." (PMID 33477364, 2021). "These latter data suggest that age-related hyperinsulinemia could be explained, primarily, by a reduction in the insulin clearance." (PMID 34054736, 2021). "Indeed, we have shown that hyperinsulinemia induces IR in dorsal root ganglia (DRG), suggestive of insulin sensitivity loss in the PNS under prediabetic conditions." (PMID 33692086, 2021). "In summary, insulin clearance reduces with age and this may contribute to age-related hyperinsulinemia." (PMID 34054736, 2021). "The finding that HFD increases the initial rate of renal insulin clearance may indicate a compensatory role for the kidney to limit peripheral hyperinsulinemia seen with HFD feeding." (PMID 33466380, 2021). "Importantly, the reductions in insulin levels were the largest in participants with worse baseline hyperinsulinemia and persisted long term after completing TRE intervention." (PMID 33466692, 2021). "Hyperinsulinemia can also upregulate hepatic lipogenesis via the insulin-Akt-mTOR signaling pathway, which can contribute to hepatic steatosis and a further decrease in insulin clearance." (PMID 34948019, 2021). "Plasma C-peptide has been found to reflect the insulin-secretory activity of pancreatic β-cells and may be used as a marker of fetal hyperinsulinemia." (PMID 33803995, 2021). "Although detailed evaluation of clinical hyperandrogenism in our cohort was beyond the scope of this study, our findings support a causal relationship between IR/hyperinsulinemia and PCOS, with ovarian hyperandrogenism resulting from excessive insulin action on the ovary." (PMID 33901270, 2021).